CCND1 (cyclin D1)
Diseases named in the same sentence as CCND1 in open-access papers (continued):
Sharing a sentence is not in itself a finding about the gene and the disease.
adenosquamous carcinoma (2 papers, 2006 to 2025). A carcinoma composed of malignant glandular cells and malignant squamous cells. "This suggests that the origin of the non-adenosquamous carcinomas in MMTV-cyclin D1 mice might be caused by cyclin D1 expression and might be repressed in the T16*MP1 bitransgenic mice." (PMID 16536875, 2006).
adrenocortical cancer (2 papers, 2020 to 2021). "Two of the studies demonstrated that RhoA was negatively associated with AKT phosphorylation and cyclin D1 in both endothelial cells and KRAS-driven adrenocortical cancer cell lines." (PMID 32244355, 2020).
ameloblastoma (2 papers, 2015 to 2024). The most common odontogenic tumor, arising from the epithelial component of the embryonic tooth and usually affecting the molar-ramus region of the mandible or maxilla. "In conclusion, we describe EGFR nuclear localization in unicystic and multicyst ameloblastomas, in association with Cyclin D1 expression." (PMID 25991665, 2015). "The confirmation of the direct binding of EGFR to the Cyclin D1 promoter in ameloblastomas can be further achieved by co-immunoprecipitation assay." (PMID 25991665, 2015). "We aimed to assess EGFR nuclear localization in Ameloblastomas and to investigate if it colocalizes with nuclear Cyclin D1." (PMID 25991665, 2015). "In addition, nuclear EGFR colocalized with Cyclin D1 in ameloblastomas." (PMID 25991665, 2015). "We found that Cyclin D1 is co-localized with EGFR in unicystic and multicystic ameloblastomas, and the co-localization is clearer in the periphery of epithelial islands (ameloblast-like cells), which are cells that proliferate more." (PMID 25991665, 2015).
anal carcinoma (2 papers, 2004 to 2016). "We found that anal carcinomas express cyclin D1 in 34% (>5% of cells stained) and cyclin E in 51% of cases." (PMID 15292923, 2004). "We studied the potential prognostic and/or predictive value of the expression of cyclin D1, cyclin E, and p21 in a large series of anal carcinomas treated by radiotherapy (RT) with or without chemotherapy in one institution." (PMID 15292923, 2004). "In conclusion, our findings indicate that pretreatment tumour expression of cyclin D1 and cyclin E has no apparent prognostic/predictive value in anal carcinomas." (PMID 15292923, 2004). "The purpose of this study was to assess the potential prognostic and/or predictive value of the expression of cyclin D1, cyclin E, and p21 protein in a series of 98 anal carcinomas (T1–4, N0–3) treated by radiotherapy with or without chemotherapy in one institution." (PMID 15292923, 2004).
anaplastic thyroid cancer (2 papers, 2022 to 2023). "Expression of cyclin D1 protein was observed at varying levels in 18/27 anaplastic thyroid cancers (67%)." (PMID 36975440, 2023).
anemia (2 papers, 2015 to 2023). A reduction in the number of red blood cells, the amount of hemoglobin, and/or the volume of packed red blood cells. "More severe anemia and increased myeloid infiltration and destruction of the spleen contributed to the earlier death of these mice, and elevated p-AKT, cyclin D1, and cyclin D3 might contribute to the development of this phenotype." (PMID 27366593, 2015).
Arthritis (2 papers, 2021 to 2024). Inflammation of a joint. "According to a study of adjuvant-induced arthritis in rats’ synovium, inhibition PPAR-γ expression by T0070907 or PPAR-γ siRNA could significantly promote the proliferation of fibroblast-like synoviocytes and expressions of c-Myc, Cyclin D1, MMP-1, and MMP-9, except for TIPM-1." (PMID 33397492, 2021).
astrocytic tumor (2 papers, 2015 to 2019). A glial tumor of the brain or spinal cord showing astrocytic differentiation. "The present study was conducted to investigate the relationship between the grade of astrocytic tumors and the expression of cyclin D1." (PMID 31583003, 2019). "According to the results obtained from this study it was found that the expression of cyclin D1 was significantly different among four different grades of astrocytic tumors." (PMID 31583003, 2019). "In this study, 100 samples diagnosed with astrocytic tumors between 2011 and 2015 that met the study’s requirements were studied and immunohistochemical staining for cyclin D1 was performed for each specimen." (PMID 31583003, 2019). "Following the results of the study, there was a significant difference (P =0.038) in the expression of the cyclin D1 marker among the four different grades of astrocytic tumors." (PMID 31583003, 2019). "Furthermore, it was also observed that the expression of cyclin D1 was significantly different (P= 0.038) among the four different grades of astrocytic tumors." (PMID 31583003, 2019). "The present study demonstrated that cyclin D1 is expressed in 60% of astrocytic tumors." (PMID 31583003, 2019). "Moreover, the expression of cyclin D1 was significantly different among different subtypes of astrocytic tumors (P- = 0.047)." (PMID 31583003, 2019). "Therefore, the present study aimed to evaluate the expression and methylation profiles of the genes CDKN2A, CDKN2B, CDC6, Bmi-1, CCND1, and RB1 in astrocytic tumors in the northern region of Brazil." (PMID 26317630, 2015). "Also, there seems to be a lack of agreement regarding the frequency of cyclin D1 in low-grade and high-grade astrocytic tumors." (PMID 31583003, 2019).
autism spectrum disorder (2 papers, 2017 to 2023). A spectrum of developmental disorders that includes autism, and Asperger syndrome. "The effect of Ccnd1 on GABA signalling and dendritic spines opens the possibility of exploring Ccnd1 functions in diseases related to the imbalance between inhibitory/excitatory signalling and dendritic spine abnormalities, such as autism spectrum disorders and epilepsy." (PMID 37684532, 2023).
bone tumor (2 papers, 2018 to 2020). "Furthermore, the anti-tumor effects of G721-0282 were observed in an xenograft in vivo model in association with the reduced expression of Chi3L1, PCNA, Cyclin D1, p-STAT3, as well as the increased expression of Chi3L1 was correlated with the p-STAT3 level in human bone tumor tissues." (PMID 31929760, 2020).
brain glioma (2 papers, 2017 to 2022). A malignant glioma that involves the brain. "However, there are still some controversies about whether the overexpression of cyclin D1 exists in brain gliomas." (PMID 35223330, 2022).
carcinosarcoma (2 papers, 2013 to 2023). A malignant tumor composed of a mixture of carcinomatous and sarcomatous elements. "Cyclin D1 gene amplification is frequently amplified in carcinosarcoma, particularly in the sarcomatous component." (PMID 23426899, 2013).
cervical tumor (2 papers, 2010 to 2017). "Furthermore, silencing of TCONS_00026907 suppressed the growth of cervical tumors and altered the expression of ELK1, p‐ELK1, C‐fos, Cyclin D1 and Bcl‐2 in vivo." (PMID 28544557, 2017).
chronic hepatitis (2 papers, 2009 to 2012). An active inflammatory process affecting the liver for more than six months. "Previously, protein levels and kinase activities of cyclin D1, E, Cdk4, cyclin A, and Wee1 were demonstrated to increase proportionally with the development of HCC, especially in the transition process from chronic hepatitis to HCC." (PMID 22539975, 2012). "In another in vitro study protein levels and activities of cyclin D1, E, Cdk4, cyclin A and Wee1 increased proportionally with the development of HCC, especially in the transition process from chronic hepatitis to HCC." (PMID 27942274, 2009).
co-infection (2 papers, 2011 to 2014). "Importantly, co-infection with AdSIRT1 largely abolished the promoting effects of IRF9 on Cyclin D1 and MMP9 promoter activities." (PMID 25319116, 2014). "Furthermore, expression of bcl–2 and cyclin D1 is overexpressed in patients with an atypical CLL and it was found also in our patients with viral coinfection." (PMID 22567048, 2011).
corticotroph adenoma (2 papers, 2021 to 2024). "In corticotroph adenomas, cyclin D1 has been proposed as biomarker of tumor aggressiveness." (PMID 33671384, 2021). "Martins and colleagues conducted a study to investigate the USP8 variant and its contribution to gene expression of cell cycle regulators including P27/CDKN1B, CCNE1, CCND1, CDK2, CDK4, and CDK6 in 32 corticotroph adenoma." (PMID 38862897, 2024).
diffuse astrocytoma (2 papers, 2016). A low-grade (WHO grade II) astrocytic neoplasm. "Significant differences were found between expression of cyclin D1 in diffuse astrocytoma and in high‐grade DIA (P = 0.001)." (PMID 27440383, 2016). "On further examination of the AP-1 target gene CCND1, we identified up-regulation of CCND1a in both pilocytic and diffuse astrocytomas compared to normal brain control." (PMID 27229157, 2016).
endometrial adenocarcinoma (2 papers, 2018 to 2022). "Our analysis of CCND1 mutations subsequently focused on two endometrial adenocarcinoma cohorts, since this cancer subtype was most frequently enriched for c-terminal cyclin D1 mutations." (PMID 29969496, 2018). "CCND1 mutations in primary endometrial adenocarcinomas of the TCGA cohort (n = 248) with corresponding patient clinico-pathological characteristics." (PMID 29969496, 2018). "First, we analyzed the primary endometrial adenocarcinoma (EMCA) cohort (n = 248) of the Cancer Genome Atlas Project (TCGA) study, in which CCND1 was mutated in 6.1% (15 of 248) cases." (PMID 29969496, 2018). "Additionally, over-expression of PRL in the Ishikawa endometrial adenocarcinoma cell line increases cyclin D1 (CCND1) mRNA levels and enhances cell cycle progression." (PMID 35773139, 2022).
endometrial stromal tumor (2 papers, 2019 to 2023). Neoplasms of the endometrial stroma that sometimes involve the myometrium. "Immunohistochemically, the round-cell component usually shows > 70% cyclin D1 nuclear staining of the tumor cells with homogenous moderate to strong intensity, in contrast to the form of scattered positive cells (< 5%) in classic JAZF1 rearranged endometrial stromal tumors." (PMID 31615558, 2019).
ependymal tumor (2 papers, 2019 to 2020). A group of neoplasms which arise from the ependymal lining of the cerebral ventricles and from the remnants of the central canal of the spinal cord. "CCND1 was also examined by FISH to explore its prognostic value for ependymal tumor patients.H3K27me3 expression in ependymal tumors was also examined by using IHC and explored the prognostic value." (PMID 31324163, 2019).
epilepsy (2 papers, 2023 to 2024). A brain disorder characterized by episodes of abnormally increased neuronal discharge resulting in transient episodes of sensory or motor neurological dysfunction, or psychic dysfunction. "The post hoc test revealed that the animals with a model of epilepsy showed a significant overexpression of Cyclin D1 in the CA2 hippocampal region compared to the C-veh rats (p < 0.001)." (PMID 39727966, 2024).
focal segmental glomerulosclerosis (2 papers, 2017 to 2021). A renal disorder characterized by sclerotic lesions in the glomeruli. "For example, in the cellular type of human FSGS (focal segmental glomerulosclerosis), studies have found absent p27, p57, and cyclin D1 expression and increased cyclin E, cyclin A, cyclin B1, CDK2, and p21." (PMID 28164134, 2017).
follicular adenoma (2 papers, 2019 to 2023). "In conclusion, Cyclin D1 and P21 can accurately identify PTC and differentiate follicular adenoma from FVPTC." (PMID 37951919, 2023). "In our study, immunohistochemical staining was used to explore the expression of Cyclin D1 and P21 in PTC, paracancerous tissue, follicular adenoma (FA) and papillary thyroid hyperplasia." (PMID 37951919, 2023). "Differential expression of Cyclin D1 and P21 in PTC and follicular adenoma may help in differential diagnosis." (PMID 37951919, 2023).
gastric cardia adenocarcinoma (2 papers, 2017 to 2019). A carcinoma that arises from glandular epithelial cells of the cardia of stomach. "Stage IIIb–IV gastric cardia adenocarcinoma patients tended to express more cyclin D1 compared with stage I–IIIa gastric cardia adenocarcinoma patients." (PMID 30974047, 2019).
glomerular disease (2 papers, 2021 to 2024). "A review of the literature reveals different glomerular diseases are associated with variable changes in cyclin D1 levels, largely depending on whether the disease presents with a proliferative or non-proliferative phenotype." (PMID 33686175, 2021). "Even if the role of GJA5, TNS1, and CCND1 in glomerular disease requires further investigation (beyond the scope of this work), they might represent a biomarker signature of progressive glomerular damage, independent of the etiology." (PMID 38516889, 2024).
hamartoma (2 papers, 2009 to 2017). A benign and excessive tumor-like growth of mature cells and normal tissues which grow in a disorganized pattern. "Although highly speculative at the moment, the observed upregulation of CCND1, in turn, might in its part explain the hamartoma finding in HLS fetuses since abnormal expression levels of CCND1 have been linked with development of cancer." (PMID 19400947, 2009).
Hepatitis (2 papers, 2017 to 2023). Inflammation of the liver. "In addition, Zhang and colleagues indicate that intravenous injection of IL-22 could enhance liver regeneration in mice with Con A-induced hepatitis after partial hepatectomy by augmentation of PCNA and cyclin D1 levels." (PMID 28578410, 2017).
hepatitis C (2 papers, 2015 to 2024). "Another chronic infection, hepatitis C virus infection, interferes with CCND1 (Cyclin D1) expression and with the cell cycle; similar pathways may be involved in Mtb infection." (PMID 26214306, 2015).
Hodgkins lymphoma (2 papers, 2016). A heterogeneous group of malignant lymphoid neoplasms of B-cell origin characterized histologically by the presence of Hodgkin and Reed-Sternberg (HRS) cells in the vast majority of cases.
idiopathic dilated cardiomyopathy (2 papers, 2023 to 2024). Decreased function of the heart associated with cardiac enlargement and congestive heart failure, of unknown cause. "A recent study suggested that CCND1 may serve as an underlying biomarker of idiopathic dilated cardiomyopathy." (PMID 38699746, 2024).
ischemic stroke (2 papers, 2022 to 2026). A stroke disorder caused by obstruction of blood flow to the brain, due to thrombotic (local blood clot formation) or embolic (due to a blood clot or other material traveling from another site) event. "The AKT/GSK3β/Cyclin D1 pathway was predicted to be a potential mechanism of FDT in intervening ischemic stroke." (PMID 41767015, 2026).
kidney failure (2 papers, 2019 to 2024). An acute or chronic condition that is characterized by the inability of the kidneys to adequately filter the blood. "A diagnostic nomogram model was constructed on the two signature genes, CDK2 and CCND1, to predict the likelihood of HF and KF occurrences via either training set or validation set, resulting in a high level of precision in forecasting heart and kidney failure risk." (PMID 39351221, 2024). "This study identifies CDK2 and CCND1 as novel biomarkers linking cell cycle regulation and inflammation in heart and kidney failure." (PMID 39351221, 2024). "Consequently, we propose that CDK2 and CCND1 may play a crucial role in immune response, potentially through signaling pathways involving neutrophils, monocytes, and resting NK cells, which are related to the pathophysiology of both heart and kidney failure." (PMID 39351221, 2024). "Indeed, Axin2, Cd44, Ccnd1 and to certain extent Myc, showed significantly lower expression in double KO compared with Pkd1 KO mice, both at 10 weeks after DCVC and at kidney failure, suggesting a reduced activation of the canonical Wnt signalling in the absence of Fjx1." (PMID 31038742, 2019).
Larynx (2 papers, 2020 to 2025). "Cyclin D1 is frequently upregulated in a significant fraction of human cancers, such as breast and respiratory tract tumors." (PMID 40178080, 2025).
latent infection (2 papers, 2021 to 2022). "This is consistent with previously reported roles of the CDKN2A/CCND1/CDK4 axis in NPC cell growth and persistent EBV latent infection in NPE cells." (PMID 34234122, 2021). "Other molecular events suspected to facilitate latent infection, and thus contribute to carcinogenesis, include hypermethylation of specific genes (e.g., RASSF1A and BLU), deactivation of p16, deactivation of lactoferrin, and upregulation of cyclin D1 production." (PMID 35804891, 2022).
Lewis lung carcinoma (2 papers, 2016 to 2023). "We found that CDDP, when administered with FGS, significantly decreased the viability and increased the apoptosis and cell cycle arrest of Lewis lung carcinoma (LLC) cells, which were associated with the increase of p21 and decreases of cyclin D1 and CDK4." (PMID 27721894, 2016). "Esculetin at concentrations up to 80 μM reduced the proliferation of Lewis lung carcinoma (LLC) cells and reduced the expression of c-myc, cyclin D1 and NF-κB." (PMID 37175299, 2023).
Lipedema (2 papers, 2022). Disorder of adipose tissue characterized by symmetric and bilateral enlargement of the lower extremities due to abnormal deposition of subcutaneous fat often in obese women. "Another gene, cyclin D1 (CCND1), has been pinned down as a potential target contributing to the hyperplastic phenotype of lipedema AT due to its positive correlation with MCE." (PMID 36551837, 2022). "Increased expression of CCND1/cyclin D1, a cell cycle regulator that is usually increased upon proliferative signals, was detected in lipedema but not control adipocytes." (PMID 36675759, 2022).
Lobular Carcinoma (2 papers, 2011 to 2022). "However, more studies are required to better understand the role of Cyclin D1 and Rb1 in lobular carcinoma before drawing any conclusions." (PMID 35743985, 2022).
Lung mucoepidermoid carcinoma (2 papers, 2019 to 2024). "In mucoepidermoid carcinoma of the lung, HMOX1 overexpression was also associated with the inhibition of cell-cycle progression proteins Cyclin D1 (CCND1) and CCND2, and the stimulated transcription of the cell-cycle arrest proteins Gastrin (GAS) and Cyclin-dependent kinase inhibitor 1C (CDKN1C)." (PMID 31717324, 2019).
lung neoplasm (2 papers, 2021). A benign or malignant, primary or metastatic neoplasm involving the lungs.
lymphoblastic lymphoma (2 papers, 2024 to 2025). A lymphoma composed of immature small to medium-sized precursor lymphoid cells (lymphoblasts). "Few cases of DLBCL can express cyclin D1(2%), but they are negative for SOX11.2,19 Lymphoblastic lymphomas must be ruled out because of their close resemblance to the blastoid cells of B-MCL." (PMID 39099606, 2024).